PIKFYVE (phosphoinositide kinase, FYVE-type zinc finger containing)
Diseases named in the same sentence as PIKFYVE in open-access papers (continued):
Sharing a sentence is not in itself a finding about the gene and the disease.
PIKFYVE also shares sentences with these, for which no sentence is quoted: colorectal cancer (2 papers); Dent-2 disease (2); endometrial cancer (2); epilepsies (2); teratocarcinoma (2); autosomal dominant cataract (1); brain arteriovenous malformation (1); cardiovascular disorder (1); co-infection (1); Cognitive impairment (1); congenital heart disease (1); congenital stromal corneal dystrophy (1); embryonal carcinoma (1); Fuchs endothelial corneal dystrophy (1); gelatinous drop-like corneal dystrophy (1); glioblastoma (1); Glucose intolerance (1); hyper-IgE syndrome (1); Immunodeficiency (1); Infertility (1); Insulin resistance (1); Intellectual disability (1); Legionella infection (1); liver cancer (1); lung carcinoma (1); mucolipidosis type IV (1); neurodevelopmental disorder (1); non-Hodgkin lymphoma (1); Parkinson disease (1); posterior polymorphous corneal dystrophy (1).
A further 6 diseases each share a sentence with PIKFYVE in 1 paper.